ETDB (embryonic testis differentiation homolog B)
Synonyms: LINC00633
Tractability: No criterion of Open Targets' tractability assessment is met for any kind of drug.
Gene: Protein-coding gene on chromosome X (135,118,955 to 135,120,526, reverse strand). Ensembl gene ENSG00000224107.
Homologues: Orthologues: chimpanzee ETDB (100% identical). Paralogues in human: ETDA (100% identical), ETDC (78% identical).